CCN1 (cellular communication network factor 1)
Diseases named in the same sentence as CCN1 in open-access papers (continued):
Sharing a sentence is not in itself a finding about the gene and the disease.
glioma (continued). "However, several reports underline a rather pro-cancerous role of S1P2: although S1P2 inhibited migration of glioma cells, it enhanced the expression of the matricellular protein CCN1/Cyr61 and stimulated glioma cell invasiveness and adhesion." (PMID 27445808, 2016). "A neutralizing antibody to CCN1 blocked S1P2-stimulated glioma invasion." (PMID 25309325, 2014). "Overexpression of CCN1 has been found to activate β-catenin translocation in several cell systems including glioma, non-small-cell lung cancer cells, and gastric epithelial cells, whereas β-catenin translocation can in turn promote CCN1 expression through Wnt signaling." (PMID 22701179, 2012). "Other studies reported a downregulation of Cyr61/CCN1 and CTGF/CCN2 expression by 2 μM VP during longer treatment in gastric cancer and glioma cell lines." (PMID 37877098, 2023). "It has been shown that CCN1, CCN2, and CCN4 all contribute to glioma progression, in agreement with our findings." (PMID 36589241, 2022). "Therefore, since our previous study indicated that CCN1 is required for mesenchymal migration, we hypothesise that glioma cells can overcome the anti-migratory drug treatment by inducing a mesenchymal–amoeboid transition (MAT) for continued migration and invasion." (PMID 35052688, 2021). "CCN1 is secreted by differentiated glioblastoma cells rather than glioma stem cells, which promotes the migration of macrophages into the tumor and contributes to GSC-dependent tumor progression." (PMID 35204054, 2022).
prostate carcinoma (33 papers, 2008 to 2025). A carcinoma that arises from epithelial cells of the prostate gland. "CCN1 has been implicated in tumorigenesis and metastasis of prostate cancer cells." (PMID 24551846, 2014). "In summary, our study provides key evidence that CCN1 plays an important role in the LPA downstream signaling in prostate cancer cells." (PMID 38545253, 2024). "In these studies, we found that eicosopentanoic acid (EPA), a dietary FFAR agonist, inhibited CCN1 induction in DU145 human prostate cancer cells." (PMID 38545253, 2024). "Our studies have shown that CCN1 is detected in human prostate cancer cells 2–6 h after the addition of LPA." (PMID 38396744, 2024). "In the current study, we observed that TUG‐891 inhibited LPA induction of CCN1 in PC‐3 prostate cancer cells." (PMID 38545253, 2024). "CCN1 and CCN2 have been implicated in responses in breast and prostate cancer cells that include proliferation, migration, survival, and tumorigenesis." (PMID 38545253, 2024). "We report for the first time, that 18:1‐LPA and 18:0 LPA have differential effects on CCN1 induction in prostate cancer cells, with 18:1‐LPA being more efficacious." (PMID 38545253, 2024). "Our previous work showed that 18:1-lysophosphatidic acid (LPA), which activates the G protein-coupled receptor LPAR1, induces CCN1 between 2–4 h in PC-3 human prostate cancer cells in a manner than enhances cell-substrate adhesion." (PMID 38396744, 2024). "Matricellular proteins such as CCN1 represent new targets for potential therapeutic interventions for prostate cancer, and in other diseases where CCN1 and/or the LPA-CCN axis play a crucial role." (PMID 38396744, 2024). "Our observations corroborate our previous studies showing that LPA induces CCN1 in human prostate cancer cell lines." (PMID 38396744, 2024). "In vivo mouse model results revealed that CCN1 increased the metastatic potential of prostate cancer cells." (PMID 24551846, 2014). "For instance, in 1998, CCN1 downregulation was reported in prostate cancer, while more recent studies showed the opposite results." (PMID 22701179, 2012). "Our observations that LPA induced CCN1 expression between 2 and 6 h, and that CCN1 was detected in ECM, led us to test whether CCN1 contributes to cell‐substrate adhesion in prostate cancer cells." (PMID 38545253, 2024). "Furthermore, the CCN1 gene rs3753793 TG and the GG genotype were significantly correlated with prostate cancer, the distribution of the GG and TG genotypes was 3.85% and 50.00%." (PMID 33906697, 2021). "Interestingly, CCN1 protein becomes elevated in 6-month old Hi-myc mice as they develop locally invasive prostate cancer." (PMID 25926554, 2015). "The correlation of CCN1 and prostate cancer bone metastases, however, needs to be confirmed." (PMID 24551846, 2014). "Our study is the first to report the proteomic changes occurring in human prostate cancer cells after LPA treatment, and the first to examine the role of CCN1." (PMID 38396744, 2024). "Several of the proteins that were up-regulated by LPA, including CCN1, play cellular roles that are potentially relevant to the effects of LPA on prostate cancer cell adhesion and migration." (PMID 38396744, 2024). "We established in the current study that both LPA and S1P induce CCN1 and CCN2 protein expression in PC‐3 human prostate cancer cells within 2 h." (PMID 38545253, 2024). "We examined the role of CCN1/CYR61, an inducible matricellular protein, in LPA‐induced signal transduction in PC‐3 human prostate cancer cells." (PMID 38545253, 2024). "Further investigations are warranted to elucidate the functional consequences of CCN1 and CCN2 induction in PC‐3 and in other prostate cancer cell lines." (PMID 38545253, 2024).
prostate carcinoma (continued). "CCN1 enhances the Fas-mediated apoptosis of skin fibroblasts and the TRAIL-induced apoptosis of prostate carcinoma cells and induces apoptosis in fibroblasts." (PMID 25187756, 2014).
lung carcinoma (31 papers, 2007 to 2025). "Once researchers have come up with the “ideal CCN1 level” on healthy humans with future studies, lung cancers like the NSCLC or those caused by the other cancer metastasis can be screened on time." (PMID 33105556, 2020). "A brief summarization of various lung cancer research in association with the CCN1 is described in this section." (PMID 33105556, 2020). "In conclusion, our study firstly demonstrated that CCN1 plays an important role in regulating the reversible resistant state of lung cancer cells." (PMID 40234387, 2025). "Despite accumulating studies conducted, the function of CCN1 in lung cancer was not fully understood and remains controversial." (PMID 40234387, 2025). "A pilot study also found that plasma CCN1 levels were significantly elevated in lung cancer patients compared with healthy controls." (PMID 40234387, 2025). "In a lung cancer model, researchers have confirmed that the CCN1 protein is involved in the occurrence of non‐small cell lung cancer, and further showed that the CCN1 plays a tumour inhibitory role in non‐small cell lung cancer." (PMID 36762748, 2023). "The regulation and function of CCN1 in lung cancer, especially in NSCLC, is still unclear and controversial." (PMID 33105556, 2020). "In lung cancer, there are many reports indicating that the CCN1 and CCN2 are negatively correlated with the prognosis of lung cancer, where the expression of CCN1 and CCN2 level is lower compared with normal matched lung tissues." (PMID 33105556, 2020). "The authors found that tumor cell-secreted CCN1 can facilitate cell migration via its direct interaction with the αVβ5 integrin in the tested lung carcinoma cell H1155 and H2122." (PMID 33105556, 2020). "β-catenin is regulated by CCN1 in esophageal squamous carcinoma and lung cancer." (PMID 25187756, 2014). "CCN1 regulates β-catenin in esophageal squamous carcinoma and lung cancer cells." (PMID 25187756, 2014). "Numerous studies have shown that the CCN1 might serve as a marker for lung cancers." (PMID 33105556, 2020). "However, CCN1 can also serve as a tumor suppressor for endometrial and lung cancers." (PMID 27167338, 2016). "Thus, the role of CCN1 in lung cancer remains unclear and deserves further investigation." (PMID 40234387, 2025). "In this review, we summarize both basic and clinical aspects of CCN1 in pulmonary diseases, including acute lung injury (ALI), chronic obstructive pulmonary disease (COPD), lung fibrosis, pulmonary arterial hypertension (PAH), lung infection, and lung cancer." (PMID 33105556, 2020).
colorectal cancer (23 papers, 2012 to 2025). A primary or metastatic malignant neoplasm that affects the colon or rectum. "Abnormalities in BATF-2 and cellular communication network factor 1 (CCN1) expressions and their correlation are closely associated with malignant behaviors of colorectal cancer cells, affecting the prognosis of patients." (PMID 34565331, 2021). "Previous studies have shown that CCN1 activates the FAK/MEK/ERK signaling pathway in colorectal cancer by binding to integrin αVβ5 to activate STAT3, a key upstream molecule known to regulate S100A8." (PMID 39659236, 2024). "CCN1 dysfunction has been observed in various cancers, including breast cancer, colorectal cancer, ovarian cancer, and pancreatic cancer." (PMID 39659236, 2024). "Looking for the CCN1 gene (a poor prognosis correlated gene in colorectal cancer), methylation heterogeneity was observed in three enhancer regions with the highest activity in Enhancer 3 which is responsible for CCN1 up-regulation." (PMID 36030244, 2022). "In colorectal cancer, CCN1 mRNA was elevated compared with normal colon, but it was reduced in more advanced stages." (PMID 22701179, 2012). "In addition, CCN1 (as well as other CCN family members) has been shown to be dysregulated in colorectal cancer and to be involved in the initiation and development as well as the promotion of this disease." (PMID 35052688, 2021). "Previous work showed that CCN1 and MACC1 cooperate to promote human colorectal cancer cell metastasis, adhesion, migration, differentiation, angiogenesis, and survival." (PMID 38396744, 2024). "Previous studies have shown a positive correlation between CCN1 and MACC1 in colorectal cancer." (PMID 38396744, 2024).
gastric cancer (23 papers, 2010 to 2025). A primary or metastatic malignant neoplasm involving the stomach. "In cancers, on the other hand, CCN1 is like a double-edged sword: in gastric cancer it was found to enhance tumorigenicity, while in squamous lung carcinoma it served the opposite role." (PMID 22701179, 2012). "From overall survival analysis, gastric cancer patients with high expression of IGFBP7, CCN2, CCN3, CCN1, CCN5 or CCN4 would have a poor survival time (all p < 0.05)." (PMID 37304887, 2023). "This study aimed to evaluate the clinical significance of cysteine-rich 61 (Cyr-61/CCN1) and cyclooxygenase-2 (COX-2), and further explored their combined prognostic significance in gastric cancer." (PMID 27457107, 2016).
rheumatoid arthritis (22 papers, 2013 to 2025). A chronic, systemic autoimmune disorder characterized by inflammation in the synovial membranes and articular surfaces. "The Serum level of CCN1 in rheumatoid arthritis patients was positively correlated with carotid intima-media thickness (CIMT)." (PMID 37046189, 2023). "Nevertheless, the role of at least CCN1 and CCN2 in rheumatoid arthritis underscores their association with the regulation of proinflammatory cytokines in the microenvironment." (PMID 34228239, 2021). "CCN1, an extracellular protein also known as cysteine-rich protein 61 (Cyr61), is a novel pro-inflammatory factor involved in the pathogenesis of rheumatoid arthritis." (PMID 28266627, 2017). "Our previous studies have shown CCN1 was overexpressed in FLS of rheumatoid arthritis (RA) patients." (PMID 35547732, 2022). "Lessons learned from the proinflammatory role of CCN1 and CCN2 in rheumatoid arthritis should prompt studies on the ability of CCN family members to affect the tumour microenvironment and immune evasion." (PMID 34228239, 2021). "Substantial evidence implicates four of the proteins (CCN1, CCN2, CCN3 and CCN4) in the inflammatory pathologies of rheumatoid arthritis (RA) and osteoarthritis (OA)." (PMID 33919365, 2021). "The CCN1 Protein of the cellular communication network (CCN) family is known to play crucial roles in angiogenesis, which not only interacts with various cytokines but also serves as an important proinflammatory cytokine in rheumatoid arthritis (RA)." (PMID 36979893, 2023).
liver fibrosis (21 papers, 2015 to 2026). "CCN1, an extracellular matrix-associated protein, is associated with carcinoma, inflammation, liver fibrosis, and even autoimmune diseases." (PMID 35547732, 2022). "On the contrary, CCN1 is upregulated during hepatic injury acting as an inhibitor of liver fibrosis by triggering induction of reactive oxygen species, cellular senescence, apoptosis and reduced TGF-β signaling in activated HSC and portal fibroblasts." (PMID 37166689, 2023). "Studies show CCN1 has also significant effects on hepatic pathogenesis, such as biliary repair, liver fibrosis and inflammation." (PMID 35547732, 2022). "We have previously shown that the matricellular protein CCN1 can induce cellular senescence in activated HSCs through direct binding to integrin α6β1, thereby accelerating matrix remodeling and resolution of liver fibrosis induced by CCl4 or cholestasis." (PMID 35708907, 2022). "Several studies showed that the other CCN family member, connective tissue growth factor (CTGF/CCN2), facilitates liver fibrosis in humans and animal models, whereas CYR61/CCN1, in contrast, promotes regression of liver fibrosis through induction of cellular senescence in hepatic myofibroblasts." (PMID 33946738, 2021). "Recent reports demonstrated that CCN1 could ameliorate skin (Jun and Lau 2010) and liver fibrosis, while promoting pro-fibrotic responses in the kidney." (PMID 28638955, 2018). "On the contrary, CCN1/CYR61 seems to have opposite effects, while the biological activity during hepatic fibrosis is somewhat controversially discussed for other CCN family members." (PMID 37166689, 2023). "CCN1, CCN2, and CCN3 have each been studied to some degree in liver fibrosis." (PMID 35038159, 2022).
glioblastoma (20 papers, 2011 to 2025). The most malignant astrocytic tumor (WHO grade IV). "In this study, high expression of CCN1 was related to cCCN1 expression and highly germline mutation of PIK3R1Met326Ile, and PIK3R1Met326Ile was found to be a prognostic factor in glioblastoma patients." (PMID 28785028, 2017). "In athymic nude mice implanted subcutaneously with human glioblastoma cells, pre-treatment with anti-CCN1 decreased TAM infiltration in the tumor and increased HSV abundance." (PMID 39196415, 2024). "Previous studies have shown that CCN1 induced by oncolytic virus infection can stimulate type I interferon reaction in glioblastoma cells, thus reducing virus replication." (PMID 35418961, 2022). "Given that CCN1-expressing glioblastomas activate an antiviral program that particularly resists HSV-1 OV, we examined how to improve the HSV-1 chassis." (PMID 34045642, 2021). "Next-generation and Sanger sequencing showed that PIK3R1Met326Ile was more frequent in the CCN1 high expression group (10/37 cases, 27.0%) than the CCN1 low expression group (3/38 cases, 7.9%) in glioblastoma." (PMID 28785028, 2017). "Previously, CCN1 expression was revealed to be an independent prognostic factor for glioblastoma patients." (PMID 28785028, 2017). "In multivariate analysis, high CCN1 expression and PIK3R1Met326Ile in glioblastoma patients were prognostic factors for OS [HR = 2.488 (1.298–4.769), p = 0.006] and [HR = 2.089 (1.020–4.277), p = 0.0439], respectively." (PMID 28785028, 2017). "The frequency of PIK3R1Met326Ile in glioblastoma was significantly higher in the CCN1 high expression group (10/37 cases, 27.0%) than the CCN1 low expression group (3/38 cases, 7.9%) (p = 0.036, Fisher’s exact test)." (PMID 28785028, 2017). "Sph-1P stimulates glioblastoma cell invasiveness in vitro via the up-regulation of the urokinase plasminogen activator, its receptor, and proinvasive molecule CCN1." (PMID 28445970, 2017). "To identify genetic alterations that correlate with CCN1 expression, we first examined CCN1 levels in glioblastoma cases." (PMID 28785028, 2017). "Antibody neutralization of CCN1 improved the glioma response to oncolytic virus therapy most dramatically in glioblastoma models with high macrophage infiltration." (PMID 28536380, 2016). "Knockdown of YAP or MRTF-A blocked induction of CCN1 (Cyr61) expression stimulated by S1P-mediated activation of GPCRs in glioblastoma cells." (PMID 28536630, 2016). "Functionally, both YAP and MRTF-A bind to the CCN1 promoter to drive S1P-stimulated glioblastoma cell proliferation." (PMID 28536630, 2016). "Activation of Cysteine-rich 61 protein (CCN1) also inhibited the oncolytic virus anti-tumor efficacy in glioblastoma through activation and infiltration of inflammatory TAMs and NK cells expressing IL-1β, IFNγ, CXCL10, and MCP-1/3." (PMID 28536380, 2016). "For example, CCN1 could activate type I IFN antiviral defense response in glioblastoma cells, which is conducive to virus clearance." (PMID 35418961, 2022). "Thus, the PIK3R1Met326Ile germline appears to be correlated with CCN1 expression and poor prognosis in glioblastoma." (PMID 28785028, 2017). "In addition, high levels of the SPHK1 enzyme and its downstream product, S1P, correlate with poor survival of glioblastoma patients, and this unusual enhancement of neural cell invasion requires upregulation of the matricellular protein CCN1/Cyr61." (PMID 21936950, 2011). "In co-cultures of macrophages and glioblastoma cells infected with HSV-1, CCN1 blockade decreased macrophage migration toward cancer cells and reduced viral clearance." (PMID 39196415, 2024). "To investigate the relationship between CCN1 and PI3K signalling in glioblastoma cases, we evaluated p-Akt levels and p85 protein expression using western blotting (n = 25) and immunohistochemistry (n = 70), respectively." (PMID 28785028, 2017).
glioblastoma (continued). "In previous research, high expression of cysteine-rich protein 61 (CCN1; also known as CYR61) correlated with a poorer prognosis in glioblastoma patients." (PMID 28785028, 2017). "Furthermore, miR-149 is also downregulated in glioblastoma cells and has been proposed to act as a tumor suppressor by targeting RAP1B, CD47, CCN1, and NXF1." (PMID 23144691, 2012).